CCND3 (cyclin D3)
Diseases named in the same sentence as CCND3 in open-access papers (continued):
Sharing a sentence is not in itself a finding about the gene and the disease.
tumor (127 papers, 2003 to 2026). "We also observed poor overall survival (p < 0.0001) of a CCND3-mutated FL patient; however, CCND3 was mutated only in the tumor tissue of this FL case." (PMID 35795062, 2022). "Most of these tumours appeared to be driven, at least in part, by individual pathogenic mutations, for example, in CCND3 (p.S259A) in RCC‐008, and two different PTEN mutations (p.C136F, p.P95R) in RCC‐015." (PMID 35231161, 2022). "It has been previously reported that cyclin D3 serves a pivotal role in the progression from G1 to S phase of the cell cycle, which is implicated in tumor progression." (PMID 35548329, 2022). "Loss of Fbxl8 results in cyclin D3 accumulation, cell cycle dysregulation and oncogene-driven transformation revealing tumor suppressor potential." (PMID 33122824, 2021). "The outcomes of this meta-analysis revealed that higher cyclin D3 level implicated an unfavorable DSS in tumor patients." (PMID 31198407, 2019). "As a pivotal regulator, cyclin D3 gives play to a crucial value in conversion from the G1 stage to the S stage of cell cycle, which is implicated in tumor progression, especially proliferationand migration." (PMID 31198407, 2019). "There is a large body of evidence that indicate that aberrantly expressing cyclin D3 have been found in different kinds of neoplasms and even linked to many malignant phenotypes." (PMID 31198407, 2019). "CCND3 expression were positively associated with ER, PR, and negatively correlated with tumor differentiation status." (PMID 30950241, 2019). "ETV4 is known to activate the transcription of multiple tumor-associated genes, including MMP genes, Cox2, Cyclin D3, and Snail, suggesting a role in tumor progression and metastasis." (PMID 29371979, 2017). "Notably, CCND3 is strongly associated with cancer, with roles as a tumor suppressor, oncogene, Cancer Census gene, and in cancer signaling." (PMID 40954493, 2025). "TMB-L (low tumor mutational load), CCND3 gene acquisition and MRE11A and ATM gene deletion mutations indicated sensitivity to PD-1/PD-L1 inhibitor combinations and the FDA-approved targeted agents Niraparib (Grade C), Olaparib (Grade C), Rucaparib (Grade C) and Talazoparib (Class C)." (PMID 38730456, 2024). "Mechanistically, BCR loss impaired mTOR-dependent anabolic control, reducing protein synthesis, while diminished Cyclin D3 abundance sensitized tumor cells to pharmacological CDK4/6 blockade." (PMID 41668618, 2026). "Vimentin, which is a canonical mesenchymal marker involved in DDP-induced tumor chemotherapy resistance 47, 48, was verified as an interacting protein of CCND3 by Co-IP and immunofluorescence assays." (PMID 39781469, 2025). "Further, a decrease in the expression of cyclin D3 involved in the induction of mitotic cell division was observed at both monitored stages of tumor formation." (PMID 40001593, 2025). "Significantly, DNA sequencing unveiled missense mutations in ABL, CCND3, CSF1R, KDR, and FGFR4, potentially contributing to tumor progression and angiogenesis in PF." (PMID 38732067, 2024). "Cyclin D3 acts as a pivotal regulator of tumor proliferation and migration by regulating G1/S transition." (PMID 39500884, 2024). "To this end, we assessed by Western blot the protein expression of several markers known to regulate tumour proliferation and invasion, such as Cyclin D3, CDK 2/4/6, TCF 1/7, Integrin beta-1, MT1-MMP, SNAIL, Vimentin, ZEB1, and ZO-1." (PMID 37887342, 2023).
tumor (continued). "More interestingly, radotinib inhibited the STAT3-targeted proteins such as Bcl-xl, Mcl-1, c-Myc, and cyclin D3 expression in IM-9 cells isolated from the tumor tissue." (PMID 35503759, 2022). "By contrast, cyclin D3 can function as a crucial regulator of differentiation and proliferation in tumor cells." (PMID 35548329, 2022). "A previous study has reported that the prognostic role of cyclin D3 in neoplasms remains controversial." (PMID 35548329, 2022). "ATF5 and cyclin D3 interact in those tumor cells through a positive feedback loop in which cyclin D3 enhances the ATF5 transcription." (PMID 35806136, 2022). "Western blotting showed that sh‐E2A significantly increased the levels of CD11b and CD14 proteins and inhibited the expression of cyclin D3 and p‐Rb compared with the control tumours." (PMID 35001521, 2022). "Cyclin D3 was shown to be overexpressed in >50% of tumour cells from splenectomy samples in all cases with a CCND3 mutation and also in 19/24 cases without a CCND3 mutation." (PMID 35158965, 2022). "A low tumor mutation burden (4–7 muts/Mb) characterized most of the testicular LCT except the peculiar metastatic case with a B4GALT5:TERT fusion and TOP1 and CCND3 amplifications that exhibited 11 muts/Mb." (PMID 33741265, 2021). "We suggest this is consistent with our conclusions that Fbxl8 regulates cyclin D3 at posttranslational level and Fbxl8 has a tumor suppressive function." (PMID 33122824, 2021). "The suppressive function of miR-138 was found to target enhancer of zeste homolog 2 (EZH2), pyruvate dehydrogenase kinase 1 and G protein-coupled receptor 124 (GPR124), SP1, SOX9, and cyclin D3 to inhibit tumor cell growth and migration." (PMID 32754587, 2020). "In previous studies, miR-138-5p has been shown to directly suppress tumour progression by targeting cyclin D3 41 and SOX4 42,43." (PMID 32292524, 2020). "Expression changes between paired tumor and normal samples also revealed the upregulation of CCND3 expression in four cases (6.6%), predominantly in HPV(−) tumors." (PMID 32224897, 2020). "Both simvastatin treatment and PTTG1 knockdown significantly attenuated the expression of c-Myc, FGF-2, and cyclin D3 and increased p21 expression, implicating that simvastatin exerts anti-tumor effects through suppressing PTTG1 function in MDA-MB-231 cells." (PMID 33250768, 2020). "Cyclin D3 and the tumor suppressor proteins p19, p21 and p27 were all reduced in the resistant tumor cells." (PMID 31010254, 2019). "The most potent combination tested: MYC, BCL2, P53dd, and CCND3 resulted in tumor formation in all mice within 38 days." (PMID 31586074, 2019). "Cyclin D3 belongs to the D-Cyclin proteins family, which can act as a crucial regulator to the differentiation and proliferation of tumor cells." (PMID 31198407, 2019). "Accordingly, PAK2 and CCND3 expression levels were markedly higher in tumor tissues than in normal tissues." (PMID 29362401, 2018). "Decreased Src phosphorylation correlated with diminished total tyrosine phosphorylation and reduced expression of Cyclin D3, a cell cycle promoter that is upregulated in many tumor cells." (PMID 25339152, 2014). "A high-level CCND3 tumor (Case OC-07) showed co-amplification of MYC and AKT2; and a high-level MYC tumor (OC-08) was co-amplified for JAK2, FGFR3, and MYB." (PMID 23289505, 2013). "Additional PEA3 family target genes implicated in neoplasia include; urokinase plasminogen activator (uPA), vimentin, cyclooxygenase-2 (COX-2), Twist, MUC4, WT1, osteopontin, mammaglobin, cyclin D3 and HER2." (PMID 20107508, 2010). "We also found that in 16% of the cases, cyclin D3 protein expression was reduced in the tumour, as compared to the adjacent normal tissue." (PMID 16012517, 2005).
tumor (continued). "Among the p27-positive tumours, cyclin D1 was the most frequently expressed cyclin either alone or in combination with cyclin E and/or cyclin D3." (PMID 12778072, 2003). "Earlier, we have shown that the cyclin D1 and E proteins were highly expressed in a large fraction of RCCs, and high cyclin D3 levels were observed in 16% of the tumours." (PMID 12778072, 2003). "In line with the previous studies, we first confirmed the role of CCND3 in promoting tumor growth." (PMID 39781469, 2025). "Reduced tRNA m7G modification on tRNAs by knocking down of METTL1 severely impaired the translation of the tumour-related genes and pathways, including cell-cycle regulator Cyclin D3 (CCND3), epidermal growth factor receptor (EGFR), phosphatidylinositol 3-kinase (PI3K) and protein kinase B (AKT)." (PMID 39723662, 2025). "As a member of the D-type cyclin family regulating the transition of the cell cycle, CCND3 has been reported to promote cell growth in various types of tumors 14, 21, 42-46; however, its roles in tumor chemotherapeutic resistance and tumor metastasis remain unexplored." (PMID 39781469, 2025). "The recurrent tumor acquired CCND3 amplification on a subsequent resection, followed by the acquisition of CDKN2A/B loss, mismatch repair deficiency, and alkylator-induced somatic hypermutation, which was identified in a liver metastasis that had a Ki67 of 50%." (PMID 38758238, 2024). "Previous studies have shown that targeting cyclin D3 could induce cell cycle arrest in various tumor types." (PMID 39500884, 2024). "To better characterize the impact of USP8 mutations on pasireotide-mediated regulation of cell cycle, we tested cyclin D3 expression in primary cultured cells from two wild-type USP8 tumors (#1 and #2) and one P720R USP8-mutated tumor (#7) exposed to pasireotide for 4 h." (PMID 35626057, 2022). "In addition, radotinib repressed expression of the activity and expression of STAT3, and its downstream proteins including Bcl-xL, Mcl-1, c-Myc, cyclin D1, and cyclin D3 in IM-9 cells isolated from the tumor tissue." (PMID 35503759, 2022). "Data thus far suggest a hypothesis wherein Fbxl8 should exhibit tumor suppressive properties reflecting its ability to antagonize cyclin D3." (PMID 33122824, 2021). "MiR-4779 by targeting PAK2 and CCND3 could suppress tumor growth by inducing apoptosis and G1/S arrest." (PMID 33330110, 2020). "But, its prognostic role of cyclin D3 in neoplasms remains controversial." (PMID 31198407, 2019). "However, overexpression of cyclin D2 failed to rescue the loss of cyclin D3 in a T-ALL initiating model, indicating that cyclin D3 is required for tumor establishment in this disease." (PMID 31226848, 2019). "However, the addition of a fourth oncogene (BCL6, BCL2, P53dd, and CCND3) led to tumor formation with a median of 112 days." (PMID 31586074, 2019). "Finally, we showed that miR-4779 negatively regulates the expression of the oncogenes PAK2 and CCND3, further suggesting that miR-4779 acts as a tumor suppressor." (PMID 29362401, 2018). "We performed RT-PCR analysis for CDK6 and CCND3 on these tumor masses." (PMID 28114995, 2017). "Interestingly, in the MSI tumor sample we detected a somatic large deletion in cyclin CCND3, which is also involved in G1-S phase progression." (PMID 28683819, 2017). "The treatment of H36 and H27 cells with these drugs induced PARP cleavage and reduced cyclin D3 expression, indicating that mutant tumor cells underwent apoptosis and cell cycle arrest, which might have synergistically retarded cell growth." (PMID 27765910, 2016).
tumor (continued). "We next determined whether the inhibition of CCND2 and CCND3 was responsible for the inhibition of tumor cell proliferation and invasion observed upon miR-503 modulation." (PMID 25860935, 2015). "The aim of our study was to evaluate the hypothesis that a combination of tumor diameter and immunohistochemical expression of cyclin D3 and Gal-3 is helpful in distinguishing between benign and malignant thyroid lesions." (PMID 26604924, 2015). "Furthermore, Pea3 activates transcription of multiple neoplasia-associated genes, including MMP genes, COX-2, Twist, osteopontin, uPA, vimentin, MUC4, WT1, mammaglobin, cyclin D3 and HER2." (PMID 20107508, 2010). "The risk associated with CCND3 rs2479717 was not significantly attenuated after adjusting for tumour stage, grade, radiotherapy, chemotherapy, adjuvant hormone therapy, and surgery (HR per rare allele carried = 1.23, 95% CI: 1.07 to 1.41; P = 0.003)." (PMID 18507837, 2008). "In cases 43 and 44, there was an elevation of cyclin D3 protein level in the tumour tissue." (PMID 16012517, 2005). "Significantly, in the early stages of tumour development, both NFKB1/RELA and PIEZO1 displayed heightened expression levels, paralleled by similar kinetic trends of proliferation‐associated genes such as CDK6, CCND1 and CCND3, as unveiled by functional pseudotime analysis of the scRNA‐seq dataset." (PMID 37983931, 2023). "Thus, we inferred that the down-regulation of C1orf132 might release the miRNAs that targeted RBL2 and CCND3 and further promote the tumor progression, which warrant further in-depth experimental research." (PMID 28587642, 2017). "Some studies reported that RBL2 and CCND3 may behave as tumor suppressors in LUAD." (PMID 28587642, 2017). "Therefore, more studies are needed to determine whether the overexpression of any of the D-type cyclins or underexpression of cyclin D3 can be related to the differentiation grade of the tumours." (PMID 16012517, 2005). "Patient OS#2 displayed a combined gain in CDK4 and CCND3 genes, and this CNV profile was present in both samples, primary tumor and recurrence, from the same patient." (PMID 41514647, 2025). "Then, to further explicit the role of CCND3 in the tumor-suppressive effect of ZNF652 in LC cells, we overexpressed CCND3 in ZNF652-OE A549 and H460 cells." (PMID 39500884, 2024). "Let-7 has been shown to inhibit the cell cycle regulators cyclin D1, cyclin D3, cyclin A and CDK4 and stop tumour growth." (PMID 38357103, 2023). "The association of highly poor survival and the presence of CCND3 mutations requires further investigation with larger FL patient cohorts as well to address whether prognostic CCND3 mutations are observed in plasma cfDNA or not as we observed CCND3 mutation in tumor tissue of only one FL case." (PMID 35795062, 2022). "Reverse transcription-quantitative PCR assays revealed that RAMP2-AS1, CD44, CCND3, NCALD and MACF1 expression was lower in tumor tissues than in normal tissues, while miR-296-5p expression was higher in tumor tissues compared with in normal tissues." (PMID 33281971, 2021). "For example, in BC tumor cells, miR-503, produced and released by endothelial cells, impairs tumor growth by targeting cyclin D2 and D3 (CCND2 and CCND3)." (PMID 34359591, 2021). "The expression levels of cyclin D1 and cyclin D3 were suppressed in the DHA treatment group, suggesting a G1 phase arrest induced by DHA on tumor cells." (PMID 33995655, 2021). "The expression levels of RAMP-AS1, miR-296-5p, CD44, CCND3, NCALD and MACF1 were detected in 40 tumor and adjacent tissue samples via RT-qPCR." (PMID 33281971, 2021).
tumor (continued). "CCND3 belongs to the cyclin D family and functions as a regulator of the CDK kinases, which are involved in the differentiation and proliferation of tumor cells." (PMID 34440000, 2021). "Roniciclib binds to and inhibits the activity of CDK1/Cyclin B, CDK2/Cyclin E, CDK4/Cyclin D1, CDK6/Cyclin D3, and CDK9/Cyclin T1, which are serine/threonine kinases playing key roles in the regulation of tumor cell proliferation and survival." (PMID 32737364, 2020). "The genes most frequently showing CNGs in HAS tumour tissues were TOP1 (50.0%), STK4 (45.5%), CDKN1B (40.9%), H3F3A (36.4%), MYC (22.7%), CCNE1 (22.7%), NFKBIA (22.7%), VEGFA (18.2%), CCND3 (13.6%), and E2F1 (13.6%)." (PMID 30989433, 2019). "In this study, we identified miR-4779 as a novel tumor suppressor miRNA and demonstrated that miR-4779 induces cancer cell apoptosis and cell cycle arrest by targeting PAK2 and CCND3 in vitro and in vivo." (PMID 29362401, 2018). "The novel tumor suppressor miR-4779 inhibits cancer cell growth via cell cycle arrest and apoptosis by directly targeting PAK2 and CCND3." (PMID 29362401, 2018). "Consistent with BCL6 protein levels, cyclin D3 protein abundance was decreased in PD REH and Nalm-27 ALL cells compared to tumor cells grown in media alone." (PMID 27015556, 2016). "Taken together, these results demonstrate that endothelial-derived miR-503 induces the inhibition of tumor cell proliferation and invasion via inhibition of CCND2 and CCND3." (PMID 25860935, 2015). "In fact, miR-16 has been reported to act as a tumor-suppressive miRNA in many cancer types, and multiple apoptosis-related genes are targeted by miR-16, including BCL-2, CCND1, CCND3, and CCNE1." (PMID 26031775, 2015). "Some of these switches occur in known tumor drivers, including PPARG, CCND3, RALGDS, MITF, PRDM1, ABI1 and MYH11, for which the switch implies a change in the protein product." (PMID 25578962, 2015). "In this context, miR-503 appears to be an antitumor miRNA secreted by endothelial cells that is able to regulate tumor cell proliferation and invasion via the inhibition of CCND2 and CCND3." (PMID 25860935, 2015). "Cyclin D3 expression was positively correlated with ER, PR and negatively correlated with HER2 and tumor differention status (p < 0.05)." (PMID 26412984, 2015). "The protein levels of Cyclin E1, Cyclin D3, Cyclin D1,Cyclin A2, CDK2 and CDK4 were significantly decreased in tumor tissues harvested from miR-188 injected mice." (PMID 25304455, 2014). "Our results showing that miR-503 targets molecules both upstream (cyclin D3) and downstream (E2F3) of Rb, an archetypal tumor suppressor, provide new insight into tumorigenesis." (PMID 23967867, 2013). "Its function results inactive in several human tumours, either by degradation via the SCF-type E3 ubiquitin ligase, Skp2 or by sequestration through Cyclin D3." (PMID 16740156, 2006). "However, the role and potential molecular mechanisms of CCND3 in DDP resistance and tumor metastasis remain less explored." (PMID 39781469, 2025). "This complex enhances mRNA translation efficiency and upregulates the expression of cell cycle-related genes, such as Cyclin D3 (CCND3) and Cyclin E1 (CCNE1), as well as genes involved in the RPTOR/ULK1/autophagy axis and the PI3K/AKT/mTOR pathway, thereby directly driving tumor cell proliferation." (PMID 41446042, 2025). "Notably, tumor sample analysis showed that RB1 protein abundance was slightly increased, while protein levels of CDK6, cyclin D3, cyclin E1, cyclin D1, SKP2, and CDK2 were significantly decreased in the combination treatment group." (PMID 34508104, 2021). "To verify whether GLI1 overexpression upregulates cell cycle regulators and the PI3K/AKT pathway in this model, we examined the expression of GLI1, p-AKT, Cyclin D3, CDK4, and Ki67 in the xenograft tumor tissues using immunohistochemical staining." (PMID 33658491, 2021).